VIM (vimentin)
Diseases named in the same sentence as VIM in open-access papers (continued):
Sharing a sentence is not in itself a finding about the gene and the disease.
tumor (continued). "Next, we detected epithelial and EMT marker gene expression in xenograft tumor tissues, and found that depletion of KLF16 in implanted cells dramatically reduced the expression of KLF16, Twist1, and mesenchymal markers vimentin, with an increase in the epithelial marker E-cadherin." (PMID 36639679, 2023). "Vimentin (VIM), snail, and e-cadherin can contribute to EMT process and promote tumor cell growth." (PMID 37962768, 2023). "There are no specific immunohistochemical reagents for this tumor; it can be positive for vimentin and CD34 and negative for S100." (PMID 37891997, 2023). "Molecular characterization of CTCs isolated from this patient by double immunofluorescence demonstrated that practically all the detected cells were CK(+)/HER2(+) and CK(+)/Vimentin(+), while the primary tumor was HER2 negative." (PMID 36690653, 2023). "Moreover, mRNA detection results of tumor tissues showed that vitamin C treatment significantly decreased the expression of VCAM-1, Vimentin, CD31 and CD44." (PMID 37283769, 2023). "Our study was focused on vimentin, a potential GBM target of tumour invasion and spread." (PMID 36765531, 2023). "It is worth noting that tumor cells 3 cluster exhibited high expression of mesenchymal markers (ZEB1, FN1, and VIM) compared to the other two tumor cell clusters, suggesting that this population of cells may have undergone epithelial-mesenchymal transition." (PMID 37007745, 2023). "Hence, CYSLTR1 and CYSLTR2 expression influenced tumor metastasis through the alteration of EMT marker expression (CDH1 and VIM)." (PMID 36834820, 2023). "Tumor Cx37 expression did not correlate with vimentin expression (p = 0.403) or Cx45 expression (p = 0.391)." (PMID 36833374, 2023). "In the process of tumor metastasis, EMT often occur to enhance its invasions, among which the downregulation of epithelial marker E‐cadherin and the activation of mesenchymal marker Vimentin are regarded as the marker changes of EMT." (PMID 36684109, 2023). "Additionally, immunohistochemical analysis revealed that the tumor cells were diffusely positive for smooth muscle actin (SMA) and vimentin." (PMID 36673024, 2023). "As we expected, PanCK(+) staining was limited to epithelial cells, while VIM(+) staining was broadly distributed in non-epithelial cells in both tumor and adjacent normal areas." (PMID 37964075, 2023). "There were no obvious human vimentin-positive cells and tumor formation at 1, 7, and 30 days after intrauterine transplantation." (PMID 37840125, 2023). "Immunohistochemical (IHC) evaluation revealed tumor cell reactivity to Vimentin, Desmin, Myo D1, and Myogenin but was non-reactive for SMA and CK7." (PMID 36777814, 2023). "In breast cancer, vimentin is conveniently abundant in connective tissue septa, especialy CAFs, but usually absent from the tumour parenchyma." (PMID 37143134, 2023). "In contrast, VIM expressions fell, particularly at the invasive tumor edge, for dCas9‐KRAB All gRNA compared to No RNA at early (29 vs 46%) and late (23 vs 59%) collection time‐points, in keeping with a mesenchymal to epithelial transition." (PMID 37217832, 2023). "Pancreatic Reck deletion was found to result in the emergence of αSMA-low/IL-6–high mesenchymal (vimentin-positive) CAF-like cells via EMT of PDAC cells, which share a similar expression pattern of marker proteins with a tumor-promoting type of CAF, termed inflammatory CAF (iCAF)." (PMID 37712427, 2023). "In this study, our system did not rely on tumor cell biomarkers such as epithelial markers (EpCAM, cytokeratins) or mesenchymal markers (vimentin, N-cadherin, E-cadherin)." (PMID 37849806, 2023). "Together, these data confirm vimentin expression by the tumor cells rather than by residual contaminating fibroblasts and suggest that LuPanc-1 cells undergo spontaneous EMT." (PMID 36831254, 2023). "Immunohistochemical(IHC) showed that the tumor cells to be positive for vimentin, focally positive for S-100, negative for calponin, SMA, SOX10." (PMID 37705036, 2023).
tumor (continued). "Immunohistochemistry corresponds to typical sex cord-stromal tumour profile (positivity for SF1, calretinin, inhibin, vimentin, often FOXL2; often oestrogen and progesterone receptor expression; and negativity or weak patchy staining for keratin, negativity for EMA, PAX8, and PAX2)." (PMID 36399188, 2023). "Immunohistochemically, the tumor cells were positive for CK, calretinin, D2-40, WT-1, and vimentin, and negative for Paird box 8, synaptophysin, chromogranin-A, inhibin-α, S-100, Melan-A, HMB45, and CD34." (PMID 38115250, 2023). "Likewise, tumor endothelial cells overexpress and secrete vimentin through type III unconventional secretion mechanisms, although cancer cells can also secrete vimentin via the use of exosomes." (PMID 37475865, 2023). "Based on these findings, we speculate that HSPA13 may promote tumorigenesis by affecting key molecules of EMT, such as decreasing E-cadherin expression and promoting vimentin expression, which in turn promotes EMT and the metastasis of tumor cells." (PMID 38062023, 2023). "Immunohistochemistry showed that the tumor cells were positive for CK7, P63, P40, CK5/6, and PCK; slightly positive for EMA; and negative for thyroid transcription factor-1 (TTF-1), napsin A, CD10, Vimentin, and smooth muscle actin." (PMID 37352028, 2023). "Here, we showed that ACPA+ RA CD8+ T cells mediate cytotoxic responses and kill DLD-1 tumor cells by releasing cytolytic granules in response to cit-vimentin or cit-H3, but not their native forms." (PMID 36658110, 2023). "In addition, vimentin is also considered a typical marker for the epithelial-to-mesenchymal transition (EMT), and its abnormal expression in tumor cells can increase their invasiveness." (PMID 36912679, 2023). "One lineage, the TGFβ-responsive myofibroblast CAF population, is located in the tumor nests, originates from stellate cells, and generates ECM mRNAs and TGFβ-induced genes such as Col1A1, Col5A1, Ctgf, smooth muscle α-2 actin (Acta2), or vimentin (Vim)." (PMID 37046676, 2023). "Furthermore, administration of α-viniferin (5 mg/kg, i.p., five days/week) in vivo resulted in the suppression of tumor growth, and decreased TUNEL positive cells and vimentin expression in nude mice bearing NCI-H460 cells." (PMID 37242510, 2023). "The reported tumours originated in the middle and lower segments of the CBD, with an average size of approximately 3.5 cm × 3.0 cm and tumour cells expressing smooth muscle actin (SMA), vimentin and ALK." (PMID 36855132, 2023). "Therefore, we examined the expression of related indicators of the epithelial–mesenchymal transformation (EMT) process (E-cadherin, N-cadherin, vimentin, and MMP9), which are closely related to tumor metastasis." (PMID 37060074, 2023). "Additionally, the positive regulation of vimentin and β‐catenin expression, and the negative regulation of E‐cadherin expression by SAMD9 were demonstrated in xenograft tumor tissues by IF analysis." (PMID 36757050, 2023). "For example, GPX3, VIM, and IGFBP3 are known to be important markers in clear cell RCC,31,32,33 but much less is known about their patterns of spatial expression within the tumor." (PMID 37426750, 2023). "In summary, Naringin mainly inhibits the invasion and metastasis of tumor cells by regulating invasion and migration-related factors and proteins such as MMP-2 and MMP-9, Snail/Twist, N-cadherin/E-cadherin, and Vimentin, and thus regulates related miRNAs, thereby inhibiting the EMT process." (PMID 37663256, 2023). "Vimentin was mostly negative in tumor cells, but variable vimentin-positive glial cells were found in the margin of the tumor, the gray matter with infiltrating tumor cells, and some minigemistocytes." (PMID 37185778, 2023). "Neoplastic cells did not express Vimentin in any of the tumor cores except that of J3T xenografts, but a weak immunopositivity to this marker was observed in J3T, Raffray and J3T-Bg perivascular cuffs." (PMID 38098992, 2023).
tumor (continued). "Notably, genetic interference of LGSN effectively suppressed tumor formation by inhibiting GCSC stemness maintenance and provoking gasdermin-D-mediated pyroptosis through vimentin degradation/NLRP3 signaling." (PMID 37612301, 2023). "On the other hand, when performing immunohistochemistry using Nestin as a marker to identify GBM cells, tumor cells (Nestin + ) presented strong reactive gliosis given the co-distribution of Vimentin (green) and GFAP (white) in the control, IKE and IKE + DHAA+Lpx conditions in the tumor area." (PMID 37752118, 2023). "Invasive tumor cells show epithelial‐to‐mesenchymal transition (EMT) characterized by reduced expression of the epithelial marker, E‐cadherin, and increased expression of mesenchymal markers, Vimentin, and Snail." (PMID 35838343, 2023). "In the validation dataset, we observed that the expression of vimentin is not always strongly detected by IHC, which can be related to tumor biology." (PMID 36769215, 2023). "In a similar manner, vimentin expression alone is insufficient to serve as the solitary marker for EMT, given that vimentin positivity is found in a range of cell types including cells of the tumor microenvironment, and immune cells, as well as CTCs." (PMID 37568766, 2023). "Finally, VIM knockdown in UMUC3 cell line increased epithelial-like features and decreased migration and invasion in vitro, decreasing tumour size and angiogenesis in vivo." (PMID 36594099, 2023). "In addition, vimentin is a widely expressed protein of the type IIIIF protein family, which increases expression in multiple tumor cell lines and tissues." (PMID 37239383, 2023). "All tumour cells were negative for vimentin, CA9, CD10, P504s, CK20, TFE3, TFEB, HMB45, ALK and FOXI1." (PMID 36816543, 2023). "Tumor cells showed immunoreactivity for β-catenin, progesterone receptor and vimentin, and were negative to synaptophysin immunostaining." (PMID 38132247, 2023). "Vimentin is a type III intermediate filament protein; it regulates the EMT of tumor cells, modulates the migration, invasion, and adhesion of tumor cells, exerts regulatory effects on angiogenesis, and may be a potential target for BC therapy." (PMID 37363395, 2023). "In this study, a CMT-1 cell line obtained from CMT-1 tumor was immune-positive to vimentin, α-SMA, p63 and negative to E-cadherin (E-cad), indicating CMT-1 cells were myoepithelial cells." (PMID 36717813, 2023). "Immunohistochemical staining of diagnostic markers showed expression of EMA, vimentin, NSE and CD99, and absence of AFP, which is comparable to the results in the primary tumor." (PMID 38201285, 2023). "Similar to vimentin, most of these studies have been done using tumor cells rather than fibroblasts." (PMID 38313431, 2023). "It is possible that the cell–cell adhesion may be weak or defective at the tumor boundary, which leads to activation of Rac1 and then promotes cell migration through the ROS–Src–STAT3–vimentin signaling cascade, as proposed in this study." (PMID 36446524, 2023). "The expression of tumor‐derived Vimentin (VIM) was nearly restricted to triple‐negative SCLC tumors (15/19, 78.9%) while YAP1 expression was distributed widely in other subtypes." (PMID 37789961, 2023). "The presence of vimentin and GFAP peptide fragments together, as well as their citrullinated forms, mainly characterized tumor tissues of lower World Health Organization (WHO) grades, such as pilocytic astrocytoma and ependymoma, while they were negligible in the most aggressive medulloblastoma." (PMID 37761239, 2023). "Therefore, the overexpression of RECK had the capacity to modulate the expression of these proteins, including E-cadherin, N-cadherin, Vimentin and MMP2, thereby exerting inhibitory effects on the migration and invasion of tumor cells." (PMID 37904179, 2023). "Increased Vimentin and CK6 levels may define a more aggressive and invasive tumor type that is resistant to PAB." (PMID 37596623, 2023).
tumor (continued). "IHC staining confirmed MELK KO and showed a reduction in the expression of Ki67, vimentin, and fibronectin in tumors from mice inoculated with MELK KO cells, suggesting that MELK KO reduces proliferation of tumor cells and inhibits EMT in vivo and thereby suppresses lung metastasis." (PMID 37377604, 2023). "Additionally, the expression of EMT-related markers was also reduced in the tumor tissue, as SHMT2 was found to have an effect on EMT in vitro, and the expression of EMT-related markers N-cadherin and vimentin were reduced in the tumor." (PMID 37108312, 2023). "Meanwhile, the results of in vitro experiments further showed that LW6 (HIF-1α inhibitor) could effectively inhibit tumor metastasis by inhibiting the expressions of HIF-1α, MMP9, N-cadherin, and Vimentin." (PMID 37239383, 2023). "Tumour cells in CMN are positive for vimentin, desmin and actin but negative for CD34 and epithelial markers, however diagnosis is primarily based on morphology." (PMID 37203959, 2023). "Imaging the tumour body and adjacent stroma in sections of human OSCC specimens, we detected single cells co-expressing EpCAM, Vimentin and CD24 in the stromal region surrounding the tumour, confirming that these cells can be detected in human tumour specimens." (PMID 37975646, 2023). "Regarding J3T-Bg-derived xenografts, the tumor core did not express any of the markers; the only observable immunostaining was that of Vimentin in perivascular cuffs." (PMID 38098992, 2023). "In these human neoplasms, the macrophage signature correlated with the expression of SNA1, FN1, ACTA2 (αSMA), SPP1 (osteopontin), COL1A1, and VIM, all genes that are specific for active CAFs, indicating that this gene signature is associated with CAF activation." (PMID 37199012, 2023). "Our present data supported the function of RNU12 in inhabiting GC tumor progression through suppressing the cell growth, migration, invasion, as well as the proliferative ability expression with CCND1, PCNA, N-cadherin, E-cadherin, Vimentin and BCL-2." (PMID 37160927, 2023). "Similarly, we captured a HER2+ and E/P-cadherin+ tumor cell cluster inside a lymph vessel (SMA+, CD31− and vimentin−) and single E-cadherin+ cells in the surrounding blood vessels (positive for CD31 and vimentin), in the second lymphovascular invasion model." (PMID 35121992, 2022). "Additionally, vimentin-keratin staining of the cultured cells showed the same epithelial to mesenchymal transition (EMT) characteristics in both the PDX and original tumor: 100% epithelial with 4% mesenchymal characteristics." (PMID 35343367, 2022). "Our data obtained using MM as experimental tumor models involving EMT, and the observations we made on curcumin-treated rats are consistent with previous reports documenting the effects of curcuminoids on vimentin and fibronectin." (PMID 35873564, 2022). "The tumor AAT β-the expression rates of catenin, vimentin, CD56, and CD10 were high." (PMID 36061381, 2022). "Then, the overexpression of circEPS15 suppressed tumor cell invasion and migration by inhibiting the TJP1/CDH2/VIM signaling pathway and retarded cell cycle progression, which was confirmed by the Transwell culture system, wound healing assays, flow cytometry and western blot assays." (PMID 35211158, 2022). "Tumor cells were negative for vimentin, CK7, smooth muscle actin, napsin A, synaptophysin, S-100, and TTF-1." (PMID 35550474, 2022). "Conversely, expression of β-catenin and vimentin almost disappeared in the tumor regions of mice with the negative CTSK expression while the expression of E-cadherin was high." (PMID 36138018, 2022). "Furthermore, N-cadherin and vimentin levels were attenuated after HOXD9 downregulation, while E-cadherin was upregulated, suggesting that HOXD9 activates EMT to enhance tumor metastasis." (PMID 36262353, 2022). "Also, western blot assay exhibited that circ_0005576 absence was able to apparently repress the expression of vimentin and MMP9 in the mice tumor tissues." (PMID 35378711, 2022).
tumor (continued). "Finally, overexpression of TPI1 increased expression of N-cadherin, vimentin, LDHA, p-mTOR, and CDCA5, whereas reduced E-cadherin in tumor tissues as demonstrated by WB." (PMID 35509067, 2022). "Indeed, mRNA and protein expression levels of an epithelial gene (CLDN1) were decreased, while those of mesenchymal (VIM) and EMT regulator (Snail, Twist1, ZEB1, and ZEB2) genes were increased in tumor cells." (PMID 35618735, 2022). "As a cytoskeletal protein in mesenchymal cells, vimentin appears only in the tumor stroma, without showing up in normal epithelial cells." (PMID 36551152, 2022). "In tumors where no NK cell invasion was detected, the vimentin signal was extremely low (mean intensity 7.1 – 20.9), while in tumor islands with high level of invasion by NK cells, the mean intensity of vimentin was 79.1 – 113.7." (PMID 36032170, 2022). "Histone H2A was more abundant in tumor compared to stroma tissues, cytokeratine 7 more abundant and vimentin less abundant in non-muscle infiltrating than in muscle-infiltrating cancers." (PMID 35439943, 2022). "In our study, vimentin upregulation, observed at the periphery of control tumor on day 7, but not on day 2, is likely indicative of a type 3 EMT process." (PMID 35406383, 2022). "Nevertheless, vimentin is intracellularly expressed in normal mesenchymal cells, such as white blood cells (WBC) and connective tissue cells, limiting its applicability as a tumor marker." (PMID 35625426, 2022). "Interestingly, circPTK2 can bind to Ser38, Ser55, and Ser82 sites of vimentin and induce EMT in vitro and in vivo and targeting of circPTK2 using shRNA significantly suppressed tumor metastasis in a xenograft mouse model of CRC." (PMID 36114510, 2022). "The important marker of EMT, vimentin, is not equally expressed in different cell lines of the same tumor." (PMID 36551152, 2022). "A pharmacological study showed that JPJD drastically inhibited the tumor invasive and migratory capability by inhibition of TGF-β/Smad signaling pathway, then modulating the EMT-related signatures containing Snail, E-cadherin, and vimentin expression levels." (PMID 35308223, 2022). "WB was further investigated to determine whether tumor-derived DNA and SIN affected the protein expression levels of E-cadherin, N-cadherin, and vimentin." (PMID 35860597, 2022). "Conversely, the adenosquamous area strongly expressed E-cadherin and lacked vimentin expression, highlighting the divergent differentiation of tumor cell-population." (PMID 35163206, 2022). "Our data showed that three out of the four G3 tumours had lower vimentin relative to that in non-tumour than the G2 tissue did." (PMID 36362433, 2022). "Immunohistochemically, some of tumour cells were strongly positive for mesenchymal cells (vimentin), whereas they were negative for myoepithelial antigen (alpha-SMA) and cytokeratin." (PMID 36043450, 2022). "Silencing of SNAIL was correlated with suppression of tumour cell invasion by reversing EMT in NSCLC while there was negative correlation between vimentin expression and overall survival in NSCLC." (PMID 35171422, 2022). "Subsequently, western blot showed that the expression levels of E-cadherin and HO-1 were notably enhanced by Lut or erastin, whereas MMP2, vimentin, GPX4, and SLC7A11 expression levels in tumor tissues treated with Lut or erastin were remarkably inhibited compared with those in the controls." (PMID 35656025, 2022). "Stains for AE1/3, GFAP, and synaptophysin were performed on the tumor involving the posterior fossa and were negative; vimentin was patchy positive." (PMID 35836290, 2022).